ACTG1 (actin gamma 1)
Diseases named in the same sentence as ACTG1 in open-access papers (continued):
Sharing a sentence is not in itself a finding about the gene and the disease.
lung carcinoma (5 papers, 2019 to 2024). "Increased expression of ACTG1 was linked to the enhanced ability of cell migration in lung adenocarcinoma and upregulated expression of ACTG1 was also markedly associated with poor prognosis in patients with lung cancer." (PMID 35757748, 2022).
coloboma (4 papers, 2013 to 2022). An abnormality in which a part of a structure in one or both eyes is missing. "This work strongly supports a causative role for a recurrent de novo nonsynonymous variant affecting ACTG1 in human coloboma, although its precise role in eye development requires further investigation." (PMID 28493397, 2017).
leukemia (4 papers, 2012 to 2025). A malignant (clonal) hematologic disorder, involving hematopoietic stem cells and characterized by the presence of primitive or atypical myeloid or lymphoid cells in the bone marrow and the blood. "In all recurrent cases, ACTG1 mRNA levels decreased, and ACTG1 mutations were also detected in VCR-resistant leukemia cell lines." (PMID 34955843, 2021).
liver cancer (4 papers, 2017 to 2023). An epithelial or non-epithelial malignant neoplasm that arises from the liver. "The results demonstrated that the expression of FCER1G, PFN1, ACTG1, PABPC1, CALM1, and RPS8 was significantly upregulated in the liver cancer cells, whereas KLRB1, LDB2, and FYN exhibited the opposite trend." (PMID 37397471, 2023). "Next, we analyzed the expression levels of ACTG1, CSNK1D, PPP1CC, and BIRC5 in HCC tissue samples in normal liver (n = 160) and liver cancer (n = 369) samples from the GEPIA dataset." (PMID 33816607, 2021). "CAP2 was coexpressed with TP53BP2, ENA/VASP in the liver cancer, and CFL1, CFL2, DSTN, ACTB, ACTG1, and ROBO1." (PMID 28423713, 2017). "In particular, it was previously reported that an increase in ACTG1 expression and a decrease in TLR3 expression could be used as biomarkers for the prognosis of liver cancer due to ethanol." (PMID 34066517, 2021).
melanoma (4 papers, 2017 to 2022). A malignant, usually aggressive tumor composed of atypical, neoplastic melanocytes. "Upon normalization of the results to A375 cells there were statistically significant differences in ACTB and ACTG1 expression for other melanoma cells lines when compared to A375 cells, however the differences were not so high varying form ca. 0.5- to 2-fold." (PMID 32326615, 2020). "Next, we checked the expression levels of ACTBL2, ACTB, and ACTG1 in five melanoma cell lines." (PMID 33558623, 2021).
microcephaly (4 papers, 2019 to 2025). A congenital or acquired developmental disorder in which the circumference of the head is smaller than normal for the person's age and sex. "In this case report, we have described deficits in the expression of essential proteins in a near-term fetus with a variant in the ACTG1 gene and demonstrating microcephaly and ACC-H by comparing this case with an age-matched control." (PMID 31231230, 2019). "Mutations in the ACTB and ACTG1 genes, encoding the ubiquitous beta- and gamma-cytoskeletal actin isoforms, respectively, cause a broad spectrum of neurodevelopmental disorders, with microcephaly as the most frequent one." (PMID 41372632, 2025).
prostate carcinoma (4 papers, 2017 to 2024). A carcinoma that arises from epithelial cells of the prostate gland. "Downregulation of ACTG1 in prostate cancer cells inhibited cell proliferation, migration, and invasion." (PMID 38339062, 2024). "For example, percentages of alterations in CAP2, CAP1, CFL1, CFL2, DSTN, ACTB, and ACTG1 genes among prostate cancer varied from 2.6–30% in individual genes (CAP2, 19%; CAP1, 13%; CFL1, 30%; CFL2, 21%; DSTN, 19%; ACTG1, 2.6%; ACTB, 21%;); the CFL1 gene was amplified predominantly in prostate cancer." (PMID 28423713, 2017).
dilated cardiomyopathy (3 papers, 2020 to 2025). Cardiomyopathy which is characterized by dilation and contractile dysfunction of the left and right ventricles. "Interestingly, KEGG analysis of upregulated proteins also implicated hypertrophic and dilated cardiomyopathy pathways, particularly through Laminin, α- and β-Dag, and ACTG1, suggesting opposing or compensatory regulatory mechanisms." (PMID 40598158, 2025). "Dilated cardiomyopathy (DCM) pathway, including Lama2, Tnnt2, Actg1, Atp2a2, Gnas, Tpm3, Itga6, Tpm1, and Pln, was enriched in the KEGG pathway." (PMID 37858115, 2023).
Lissencephaly (3 papers, 2021 to 2024). A spectrum of malformations of cortical development caused by insufficient neuronal migration that subsumes the terms agyria, pachygyria and subcortical band heterotopia. "The genetic factors known to cause lissencephaly are DCX (double cortin), gene TUBA1A (tubulin alpha 1a), ACTB (actin beta), ACTG1 (actin gamma 1), and ARX (aristaless-related homeobox)." (PMID 39040723, 2024).
lymphoid cancers (3 papers, 2020 to 2024). "In the realm of hematological malignancies, mutations in actin genes ACTB and ACTG1 are predominantly linked to lymphoid cancers." (PMID 38240686, 2024). "Using patient data available at cBioPortal we show that mutations in ACTB and ACTG1 in hematological cancers all occur in lymphoid cancers." (PMID 32349449, 2020). "Indeed, focusing on the absolute counts instead of the frequencies reveals that all 58 patients with mutations in ACTB and/or ACTG1 suffer from a type of lymphoid cancer." (PMID 32349449, 2020). "Within the different types of lymphoid cancers ACTB mutations are most frequent in diffuse large B-cell lymphoma (DLBCL) and ACTG1 mutations in multiple myeloma." (PMID 32349449, 2020). "To identify subtypes of lymphoid cancers potentially enriched in somatic mutations in ACTB and/or ACTG1 we selected ‘cancer type detailed’ in the ‘cancer types summary’ tab after querying the lymphoid cancers in cBioPortal." (PMID 32349449, 2020). "Compared to other lymphoid cancer types, mutations in ACTB and ACTG1 are most frequent in DLBCL and multiple myeloma, respectively." (PMID 32349449, 2020). "We focused on ACTB and ACTG1 in blood cancers by selecting studies on lymphoid cancers and myeloid cancers in cBioPortal." (PMID 32349449, 2020). "Within hematological cancers, mutations in ACTB and ACTG1 are exclusively associated with lymphoid cancers and not with myeloid cancers." (PMID 32349449, 2020). "Within studies on hematological cancers, mutations in ACTB and ACTG1 are associated with lymphoid cancers since none have currently been reported in myeloid cancers." (PMID 32349449, 2020).
Obesity (3 papers, 2023 to 2025). Accumulation of substantial excess body fat. "We found that HMBA bound to MYH9 and ACTG1, which were required for the anti‐obesity effects of HMBA in both NPY‐expressing and POMC‐expressing neurons." (PMID 37984341, 2023). "Collectively, the reducing effects of HMBA on body weight and food intake were completely abrogated by silencing of Myh9 and Actg1 in AgRP and POMC neurons, suggesting that MYH9 and ACTG1 are required for the anti‐obesity effects of HMBA." (PMID 37984341, 2023). "HMBA ameliorates obesity by MYH9- and ACTG1-dependent regulation of hypothalamic neuropeptides." (PMID 39408647, 2024).
squamous cell carcinoma (3 papers, 2020 to 2025). A carcinoma arising from squamous epithelial cells. "Indeed, the genes ACTG1, CAV1, MYLK, and PAK were also found to be deregulated in a transcriptomic analysis of epidermoid carcinoma cells A431, indicating that BCL6 modulates the invasion capacity of physiological and malignant components through similar molecular mechanisms." (PMID 33182312, 2020).
bladder cancer (2 papers, 2024 to 2025). "Similarly, a potential mechanism by which ISO inhibits bladder cancer cell proliferation, migration, and invasion may be through downregulation of ACTG1." (PMID 38339062, 2024). "To investigate the protein expression profiles of six genes (ABCA7, HOOK2, JUNB, RHOB, VMP1, and ACTG1) that significantly impact both DSS and PFI in bladder cancer patients, we conducted Western blot analyses using SV-HUC-1 and 5637 cell lines." (PMID 40574864, 2025).
Cognitive impairment (2 papers, 2022). Abnormal cognition is characterized by deficits in thinking, reasoning, or remembering. "Here, actin encoded by Actg1 is downregulated in the AI, which may contribute to cognitive impairment in VPA-exposed rats." (PMID 36474209, 2022).
dry eye (2 papers, 2019 to 2024). "Of these proteins, CEACAM7 and RARRES1 have not yet been connected to ocular surface condition and while ACTG1 is an interesting protein, it has so far been only connected to treatment effects of dry eye." (PMID 30976209, 2019). "The role of ACTG1 in postoperative healing period is not clear, but it has previously been associated with keratoconus and treatment effect of dry eye." (PMID 38368345, 2024).
E. coli infection (2 papers, 2019 to 2021). "Enrichment analysis using the KEGG database revealed the significant participation of detected proteins in pathogenic E. coli infection (ACTG1, TUBA1C, TUBA4A, TUBB, TUBB8, and YWHAZ), which may indicate microbiota changes associated with being in space." (PMID 31547269, 2019). "The expression of six genes (KRT18, ARPC5L, ACTG1, ARPC2, EZR, and YWHAZ) related to pathogenic E. coli infection was simultaneously increased with TNFRSF11B overexpression via gene set enrichment analysis (GSEA)." (PMID 34938284, 2021). "In addition, only six genes (KRT18, ARPC5L, ACTG1, ARPC2, EZR, and YWHAZ) related to pathogenic E. coli infection were simultaneously increased in both GSEA studies; these genes are mostly involved in focal adhesion, as determined via GO analysis." (PMID 34938284, 2021).
glioblastoma (2 papers, 2021). The most malignant astrocytic tumor (WHO grade IV). "At present, there are few studies on COX10-AS1, some studies show that it sponged miR-361-5p to enhance ACTG1 expression and accelerated tumorigenesis in glioblastoma." (PMID 34323174, 2021).
glioma (2 papers, 2022 to 2025). A benign or malignant brain and spinal cord tumor that arises from glial cells (astrocytes, oligodendrocytes, ependymal cells). "In a follow up study by the same group using C6 glioma cells, 4 of our hits (Tubb1, Tubb5, Actg1 and Kif5b) were present out of a list of 22 enriched proteins." (PMID 41142754, 2025).
multiple myeloma (2 papers, 2020 to 2024). "For only a few of the congenital mutations functional and/or biochemical consequences have been studied and, interestingly, some of these map close to the positions of the mutations in ACTB or ACTG1 in DLBCL or multiple myeloma." (PMID 32349449, 2020). "Mutations in ACTG1 are largely associated with multiple myeloma (in cBioPortal referred to as plasma cell myeloma)." (PMID 32349449, 2020). "ACTB mutations are found primarily in DLBCL and ACTG1 mutations are most frequent in multiple myeloma." (PMID 32349449, 2020). "In contrast, most of the mutations in ACTB and ACTG1 in DLCBL and multiple myeloma are concentrated in the N-terminal half of the sequence." (PMID 32349449, 2020). "The DLBCL mutations in ACTG1 map mostly to SD1 and SD2 whereas these in multiple myeloma are almost exclusively in SD1." (PMID 32349449, 2020). "In addition, in three independent studies on multiple myeloma, ACTG1 was identified as one of the most frequently mutated genes in this hematological cancer involving plasma cells and it even met the criteria for potentially being a candidate driver gene in multiple myeloma." (PMID 32349449, 2020). "Using the crystal structure of the ACTB monomer, we mapped the amino acid alterations in ACTB and ACTG1 resulting from missense mutations observed in the DLBCL and multiple myeloma patient samples." (PMID 32349449, 2020). "Together, this suggests that ACTB and ACTG1 mutations are potentially more than passenger mutations in DLBCL and multiple myeloma, respectively." (PMID 32349449, 2020). "Of note is that, in a multiple myeloma study, ACTG1 met the criteria for being a driver in this disease although this was not explicitly mentioned by the authors)." (PMID 32349449, 2020). "This or the causality of the observed mutations in DLBCL and multiple myeloma need further investigation by future screening studies of additional patients and functional studies of ACTB or ACTG1 mutants in appropriate models or patient material." (PMID 32349449, 2020). "In a later study, ACTG1 was also recognized as a potential driver in multiple myeloma." (PMID 32349449, 2020). "In between DLBCL and multiple myeloma, there are no common mutational sites found in ACTB or ACTG1." (PMID 32349449, 2020).
nonsyndromic hearing loss (2 papers, 2014 to 2024). "In roof/epithelial (CD−M1), Myo6 and Actg1 were associated with nonsyndromic hearing loss (NSHL), Hsd17b4 with Perrault syndrome, Ednrb and Edn3 with Waardenburg syndrome, and Actg1 with Baraitser–Winter syndrome." (PMID 39684410, 2024). "Of the 23 probands, six had mutations in DFNA genes [WFS1 (n = 2), COCH, ACTG1, TMC1, and POU4F3] known to cause autosomal dominant nonsyndromic hearing loss." (PMID 25388789, 2014).
osteosarcoma (2 papers, 2015 to 2025). A usually aggressive malignant bone-forming mesenchymal neoplasm, predominantly affecting adolescents and young adults. "In osteosarcoma, abnormal expression of ACTG1 may enhance tumor invasion by affecting microtubule stability, thus negatively affecting patient prognosis." (PMID 40166371, 2025).
Parkinson disease (2 papers, 2020 to 2022). A progressive degenerative disorder of the central nervous system characterized by loss of dopamine producing neurons in the substantia nigra and the presence of Lewy bodies in the substantia nigra and locus coeruleus. "Here, we demonstrated that capsaicin can protect against 6-OHDA-induced Parkinson's disease and reduce the apoptosis rate by regulating Actg1 and Gsta2 in a cell model." (PMID 32537633, 2020). "The present study showed that regulation of Actg1 and Gsta2 is the possible mechanism by which capsaicin alleviates apoptosis in a cell model of 6-OHDA-induced Parkinson's disease." (PMID 32537633, 2020). "Here, our experiments demonstrated that overexpression of Actg1 (actin gamma 1) and Gsta2 increased apoptosis in a cell model of 6-OHDA-induced Parkinson's disease." (PMID 32537633, 2020). "CCK-8 detection and flow cytometry demonstrated that overexpression of Actg1 and Gsta2 increased apoptosis in the 6-OHDA-induced Parkinson's disease cell model." (PMID 32537633, 2020).
Sepsis (2 papers, 2023 to 2026). Sepsis is defined as life-threatening organ dysfunction caused by a dysregulated host response to infection. "These same authors blocked ACTG1 with RNA interference, in vitro, and found a decrease in apoptosis, suggesting that this protein may be a promising therapeutic target in sepsis." (PMID 41316847, 2026). "Four proteins showed a >3-fold difference between HLH and sepsis: actin, cytoplasmic 1 (ACTB); actin, cytoplasmic 2 (ACTG1); CD16a antigen (FCGR3A); and plastin-2 (LCP1)." (PMID 37653176, 2023). "Similarly, our study showed that IFN-γ signaling pathway proteins (ACTG1, HSP90AB1, and VCAM1) were significantly higher in patients with HLH than in patients with sepsis." (PMID 37653176, 2023).
Skeletal myopathy (2 papers, 2013 to 2023). "Although loss of gamma cyto-actin did not impede muscle development, muscle-specific gamma cyto-actin knockout (Actg1–/–) mice exhibited overt symptoms of skeletal myopathy including decreased mobility, limb weakness, and joint contractures." (PMID 24265776, 2013). "Other studies found that knocking out ACTG1 leads to growth delay and skeletal myopathy in mice." (PMID 38002977, 2023).
AIDS (1 paper, 2010). A syndrome resulting from the acquired deficiency of cellular immunity caused by the human immunodeficiency virus (HIV). "For example, the host protein interaction net such as VCL - TLN1 - actin, cytoplasmic 2(ACTG1) - FLNA was found to interact with nef and pol (HIV function proteins), and be substantially up-regulated in HIV/AIDS patients." (PMID 20222986, 2010).
amoebiasis (1 paper, 2025). "Notably, infection-related pathways such as amoebiasis and Vibrio cholerae infection (e.g. GNAS, ACTG1 and HSPB1; adjusted P<0.01) were also identified." (PMID 40989927, 2025).
asthma (1 paper, 2025). "In asthma model guinea pigs, ACTG1 expression significantly decreased compared to controls, while the expression levels of ACTB, ACTA2, and MYL9 significantly increased (p < 0.01, n = 5, each group)." (PMID 40980809, 2025). "It is possible that the reduction of ACTG1 in asthma may promote the upregulation of ACTA2, and probably ACTB, thereby enhancing AHR through the activation of inhibitory pathways that prevent muscle relaxation, such as those regulated by ROCK." (PMID 40980809, 2025). "Thus, this study demonstrated that the expression of the main smooth muscle actins, namely, ACTA2, ACTB, and ACTG1, was modified in the bronchial smooth muscle—a crucial tissue in asthma —of guinea pigs in an asthma model." (PMID 40980809, 2025). "Therefore, the regulation of not only ACTA2 but also ACTG1 may be involved in the increased contraction of ASM in asthma." (PMID 40980809, 2025). "Within this context, our findings suggest that ACTG1 and ACTB play interdependent roles in regulating AHR in asthma." (PMID 40980809, 2025). "This study confirmed the expression of peptides corresponding to ACTA2, ACTB, ACTG1, MYH11, FLNA, MYL9, and TAGLN in both control guinea pigs and the asthma model." (PMID 40980809, 2025). "Based on immunohistochemistry data, the interactomes related to the expression of MYH11, MYL9, ACTG1, ACTA2, ACTB, TAGLN, and FLNA in the bronchial smooth muscle of guinea pigs in an asthma model were generated." (PMID 40980809, 2025). "ACTG1 exhibits a differential behavior compared to ACTB and ACTA2 in the present study, as its decrease correlates with AHR in asthma." (PMID 40980809, 2025).
cerebrofrontofacial syndrome (1 paper, 2023). "ACTG1 gene, encoding γ-actins, is the responsive gene of DFNA20/26 and Baraitser–Winter cerebrofrontofacial syndrome." (PMID 38027523, 2023).
cervical cancer (1 paper, 2022). A primary or metastatic malignant neoplasm involving the cervix. "The impact of γ-actin to the tumor development was highlighted recently by the several studies, where a strong ACTG1 expression was associated with an increase of metastatic potential and worse prognosis for hepatocellular carcinomas, colorectal, lung and cervical cancers." (PMID 35721191, 2022). "5-Hydroxymethylcytosine (5hmC) at the gene of ACTG1 between other selected genes was sensitive and specific to cervical cancer malignancy." (PMID 35721191, 2022).
Cirrhosis (1 paper, 2025). A chronic disorder of the liver in which liver tissue becomes scarred and is partially replaced by regenerative nodules and fibrotic tissue resulting in loss of liver function. "Additionally, anoikis-related genes such as ACTG1, STAT1, and CCR7 have been identified as biomarkers for cirrhosis, providing insights into the disease’s immune landscape and potential for targeted therapies." (PMID 41223189, 2025).
developmental disabilities (1 paper, 2024). "Patients carrying mutations in ACTB or ACTG1 predominately suffer from developmental disabilities, which can be directly linked to cortical malformations of varying severity." (PMID 38446501, 2024).
endometrial cancer (1 paper, 2020). Primary or metastatic malignant neoplasm involving the endometrium (mucous membrane that lines the endometrial cavity). "We found that ACTG1 gains were slightly enriched in type II endometrial cancers." (PMID 33217970, 2020). "We also examined ACTG1 gains with consideration of type I vs. type II endometrial cancers." (PMID 33217970, 2020).